STAT3 (signal transducer and activator of transcription 3)
Diseases named in the same sentence as STAT3 in open-access papers (continued):
Sharing a sentence is not in itself a finding about the gene and the disease.
glioma (continued). "Hence, SD‐36 indeed effectively induced degradation of STAT3 protein, its putative target, in human glioma cells." (PMID 34291563, 2021). "Abnormal expression of STAT3 is involved in the process of cell proliferation, migration, invasion, immunosuppression, angiogenesis, dryness maintenance, and resistance to radiotherapy and chemotherapy in glioma." (PMID 34425834, 2021). "In addition, STAT3 regulates and selects macrophages, which are primary glioma-infiltrating immune cells, and STAT3 is attracting attention as a major regulator of GBM anticancer effects." (PMID 34065991, 2021). "Therefore, human and canine osteosarcoma, and human glioma cells showed increased cell death response when exposed to STAT3 inhibitor drugs." (PMID 33544704, 2021). "In agreement with this, the inhibition of STAT3 (Signal Transducer and Activator of Transcription 3) and p38 pathways promote DC differentiation in the tumor microenvironment and increased allogeneic T-cell reactivity against glioma, melanoma cells, or multiple myeloma." (PMID 33922633, 2021). "Moreover, the continuous high expression and activation of STAT3 is an important factor in the occurrence and development of glioma." (PMID 34425834, 2021). "In conclusion, our findings above suggested that anticarin β effectively and selectively suppress the growth, proliferation, and stemness of human glioma cells by inducing apoptosis and DNA damage, which likely through modulation of STAT3, Akt, MAPKs pathways, and apoptotic-related proteins." (PMID 34408983, 2021). "ANXA2 also regulates glioma cell proliferation via the STAT3‐cyclin D1 pathway." (PMID 34047479, 2021). "NC can inhibit the EMT process and glioma stem cell characteristics of glioma cells via modulation of JAK2/STAT3 signaling, suggesting that NC may be a potential anti‐glioma drug." (PMID 33788424, 2021). "Based on these findings, whether SERPINA3 affects CD4+ T cells in glioma by affecting STAT3 should be further investigated." (PMID 34449972, 2021). "The level of p-STAT3 was higher in glioma cell lines compared with normal brain tissues." (PMID 34195079, 2021). "Indeed, signal transducer and activator of transcription 3 (STAT3) inhibition has been associated with a decreased level of IL-6 in melanoma and glioma cell lines." (PMID 33692796, 2021). "Therefore, in addition to ceRNA mechanisms, studies should explore other mechanisms by which lncRNAs and circRNAs regulate the STAT3 signalling pathway in gliomas." (PMID 34425834, 2021). "The JAK/STAT3 signaling pathway has previously been shown to be critical in glioma." (PMID 34141710, 2021). "In addition, IL-22 treated glioma cells triggered activation of STAT3 and PI3K-Akt phosphorylation and increased anti-apoptotic protein Bcl-xL level." (PMID 34439380, 2021). "Thus, suppression of miR-2276 by oncogenic STAT3 establishes it as a tumor suppressive miRNA in gliomas." (PMID 34141710, 2021). "Taken together, these results suggest that H2O2 treatment could induce CYB561D2 expression and activate STAT3 in glioma cells." (PMID 34372858, 2021). "STAT3 regulates the migration and invasion of glioma cells by targeting MMP2, MMP9, SNAIL, etc.." (PMID 34425834, 2021). "To investigate whether CYB561D2-activated STAT3 induces the expression of immunosuppressive genes in gliomas, we measured protein expression of FASLG, TGF-β2, CD70, PD-L1, PD-L2, CCL2 and TDO2 in U251 and U87 transfected with CYB561D2 plasmid for 48 h." (PMID 34372858, 2021). "Napabucasin is another recently characterized orally bioavailable small-molecule STAT3 inhibitor capable of inducing cell cycle arrest, apoptosis, and the reduction of markers of stemness, leading to improved survival in an orthotopic murine glioma model." (PMID 33498872, 2021). "Additionally, miR-21 promoted glioma cell growth and the expression of human telomerase reverse transcriptase (hTERT) in a STAT3-dependent manner." (PMID 34425834, 2021).
glioma (continued). "Also, silencing MMP-2 in glioma cell lines impaired α5, β1 integrin, IL-6 signaling, and STAT3 phosphorylation, thus hindering the proliferation and growth of glioma." (PMID 33854965, 2021). "FBLIM1 promotes cell migration and invasion in human glioma by altering the PLC-γ/STAT3 signaling pathway and could be used as a molecular marker for early diagnosis in glioma patients." (PMID 33808029, 2021). "Our findings suggest that IL-6 and miR-155-3p may be novel biomarkers for diagnosing glioma and that treatments targeting autophagy and the STAT3 pathway may contribute to antitumor immunotherapy." (PMID 33828078, 2021). "Given the intrinsic phenotypic plasticity of glioma cells, we sought to determine whether the STAT3 signaling axis could be a potential compensatory mechanism that is adopted by surviving HDAC1-deficient hGSCs." (PMID 34494550, 2021). "Considering that the JAK2/STAT3 signaling pathway is overactivated in glioma cells, we speculate that fraxetin may play an antiglioma effect by inhibiting JAK2/STAT3 signaling." (PMID 33959183, 2021). "Stat3 is a critical mediator of immune related responses in gliomas." (PMID 34425907, 2021). "Thus, SD‐36 effectively impedes the growth of glioma xenografts by reducing STAT3 and Mcl‐1 levels and enhancing apoptosis in vivo." (PMID 34291563, 2021). "We first tested the responses of U87 and U251 glioma cell lines to the STAT3 degrader SD‐36 and Stattic using a 3‐day cell viability assay and found that the survival rate of these cell lines decreased more strongly with SD‐36 in general than Stattic treatment." (PMID 34291563, 2021). "Furthermore, STAT3 inhibition in glioma results in a decrease in TReg prevalence, enhanced T- and antigen-presenting cell activation, and increased production of anti-tumor cytokines." (PMID 34483843, 2021). "Knockdown of LIF significantly reduced nuclear level of phosphorylated STAT3 in glioma cells." (PMID 34729101, 2021). "The current study has clearly shown that the novel STAT3 degrader SD‐3615 exhibits much more potent activity than Stattic in decreasing the survival of a panel of human cell lines for glioma, in apoptotic induction of these cells and in inhibiting the growth of glioma xenografts and PDXs in vivo." (PMID 34291563, 2021). "In contrast, CYB561D2 over-expression reduced survival rate in intracranial glioma model and this effect could be blocked by dominant negative-STAT3." (PMID 34372858, 2021). "Inhibition of CLCF1 to reduce phosphorylation of STAT3 may be an effective strategy for treating glioma with mutant PTEN." (PMID 34336645, 2021). "Moreover, the expression of miR-182-5p was markedly increased and positively correlated with the expression of activated STAT3 in glioma cell lines." (PMID 34425834, 2021). "STAT3 plays an important role in multiple malignant cases, especially in glioma." (PMID 33299498, 2020). "The results indicated that DEGs are enriched in immune-related biological processes, including IL2/STAT5, IL6/JAK/STAT3, and Interferon-γ response signaling and the two categories identified by consensus clustering are correlated with immune infiltration of glioma." (PMID 33123464, 2020). "STAT3 expression promotes tumour incidence in combination with PDGF in a glioma mouse model." (PMID 32218467, 2020). "Thus, Imaging-Community-AMARETTO (Appendix Fig A1) identified THBS1 and MAP2 as novel master drivers across the three STAT3, AHR, CCR2, and OLIG2 communities that provide new insights into how these distinct key mechanisms are linked in glioma." (PMID 32383980, 2020). "STAT3 exhibited markedly up‐regulated levels in glioma (adj." (PMID 31868319, 2020). "Another signaling pathway that has long been associated with apoptosis and survival of tumor cells, the STAT3 signaling pathway, which is activated by phosphorylation in glioma cells and has regulatory functions in terms of proliferation, angiogenesis, tumor migration, invasion." (PMID 32463472, 2020).
glioma (continued). "Importantly, STAT3 mRNA expression was related to chemoradiation resistance in pGBM and primary glioma (pGlioma)." (PMID 32483429, 2020). "miR-506 also functioned as a tumor suppressor in glioma by targeting STAT3, suggesting that miR-506 may be a potential target in the treatment of human glioma." (PMID 33336050, 2020). "Besides, a recent study of glioma found that RPN2 repressed the radiosensitivity of glioma cells by activating STAT3 signal transduction." (PMID 33087705, 2020). "We systematically evaluated survival data for 1,070 glioma patients included in 12 different trials and came to the conclusion that the expression of STAT3/p-STAT3 may be a marker of poor prognosis in glioma." (PMID 33299498, 2020). "Emerging studies have shown STAT3 and its phosphorylation have similar functions in tumors, including in glioma, and given this consideration, we conducted a meta-analysis of STAT3/p-STAT3 to identify any direct correlations with glioma patient prognosis." (PMID 33299498, 2020). "CRNDE promoted malignant progression of glioma by STAT3 and EGFR." (PMID 33178271, 2020). "Fewer patients with glioma, liver cancer, melanoma, and testis cancer could detect medium or high expression of STAT3." (PMID 32486001, 2020). "Although several biomarkers such as MGMT, STAT3, and APNG have been explored to be associated with the sensitivity of TMZ, TMZ resistance in gliomas is still incompletely elaborated." (PMID 33362537, 2020). "Moreover, the over‐expression of MC‐let‐7a‐1 ~ let‐7d was observed to enhance cell apoptosis and autophagy, and impeded cell proliferation in glioma, which was blocked via the down‐regulation of STAT3." (PMID 31868319, 2020). "In conclusion, we suggested STAT3/p-STAT3 was associated with poor prognosis in patients with glioma, which indicated that STAT3/p-STAT3 might be a valuable prognostic biomarker and a promising therapeutic target for glioma." (PMID 33299498, 2020). "Moreover, continuous cytokine-mediated STAT3 stimulation has been reported in many cases of solid tumors—head and neck cancer, melanoma, prostate, breast, colon, and gliomas." (PMID 33158194, 2020). "The results showed that STAT3 expression was increased in the three types of glioma tissues." (PMID 31868319, 2020). "And silencing hnRNPA2/B1 inhibits STAT3 phosphorylation and decreases STAT3 activity; Therefore, we believe that the role of hnRNPA2/B1 in the development of glioma may be related to the AKT pathway and STAT3 pathway." (PMID 32463472, 2020). "Therefore, our results underlined that miR cluster MC‐let‐7a‐1 ~ let‐7d exerts an anti‐oncogenic function on glioma by down‐regulating STAT3." (PMID 31868319, 2020). "Our results are consistent with these findings and suggest that ADV infection could trigger TLR9-MYD88 signaling and lead to the formation of GSCs from primary glioma cells in a STAT3-dependent way." (PMID 32843056, 2020). "In addition, p-STAT3 was reported to affect the occurrence, development, and even prognosis of glioma." (PMID 33299498, 2020). "On the other hand, genetic knockout of ATM in human glioma cells showed significantly less expression of CD133, Oct4, Nestin, and activated STAT3, four important markers of glioma CSCs, suggesting that ATM activation were directly responsible for glioma CSC maintenance." (PMID 32566127, 2020). "In addition, Cai, Zhu & Gong (2018) found that miR-148a regulated STAT3 pathway activity by directly targeting CADM1 to promote glioma cell growth and metastasis." (PMID 33062427, 2020). "In the subsequent experiment, we intended to verify whether the miR cluster MC‐let‐7a‐1 ~ let‐7d participated in autophagy and apoptosis of glioma cells by targeting STAT3." (PMID 31868319, 2020). "The effect of STAT3 on the development of glioma was detected both in vitro and in vivo." (PMID 31868319, 2020).
glioma (continued). "In addition, STAT3 activation is also commonly found in human cancers including gliomas through modulating genes involved in cell growth, apoptosis, migration and invasion." (PMID 32517717, 2020). "Our study shows that STAT3/p-STAT3 expression is related to poor glioma prognosis." (PMID 33299498, 2020). "Moreover, previous studies have shown that inhibiting STAT3 activation suppresses radiation-induced PMT in glioma." (PMID 33028341, 2020). "Hence, the study was designed to investigate the mechanism by which the miR cluster MC‐let‐7a‐1 ~ let‐7d influences the autophagy of glioma cells in connection to STAT3." (PMID 31868319, 2020). "The influence of STAT3 on the progression of glioma was assessed in vivo." (PMID 31868319, 2020). "Furthermore, GSK126, a selective small molecule Ezh2 inhibitor that is structurally related to GSK503, has been shown to decrease levels of phosphorylated STAT3 (pSTAT3) in glioma cells that resemble stem cells." (PMID 32503684, 2020). "Therefore, it appeared mechanistically ATM promotes stemness in glioma cells by phosphorylating and activating STAT3, which has been to be a crucial factor in glioma stem cells." (PMID 32566127, 2020). "In addition, the levels of E-cadherin, connexin-43, and GFAP, which are abundantly expressed in astrocytes and at a low level in glioma cells, were upregulated; p-STAT3 has been found to initiate the promoter of GFAP." (PMID 33227992, 2020). "But the expression of p-STAT3 was positively correlated with Nanog expression in glioma samples." (PMID 31534499, 2019). "Furthermore, STAT3-targeting agents to generate potent anti-glioma effects in the clinic remain to be further explored." (PMID 31277685, 2019). "Consequently, we and others previously demonstrated that targeting Stat3 by upstream signaling inhibitors of the Stat3 pathway decreases glioma cell proliferation and migration in vitro and prolongs overall survival of tumor-bearing mice in vivo." (PMID 30857197, 2019). "The aberrant expression of STAT3 has been implicated in GBM development and progression and has been suggested to be a master regulator of the mesenchymal cum malignant transformation of gliomas." (PMID 31783691, 2019). "We next investigated whether targeting of NF-κB or STAT3 would exert an effect on SRT2183-induced glioma cell death." (PMID 31319814, 2019). "Stat3 is activated in many other human cancers in addition to gliomas." (PMID 30857197, 2019). "Additionally, NF-κB has been shown to drive mesenchymal transformation in glioma stem cells by induction of master transcription factors STAT3, CEBP-β and TAZ, which can subsequently contribute to resistance to radiation and chemotherapy." (PMID 30621209, 2019). "Our current results showed that AP-2α could downregulate IL6 expression and block the Jak2/STAT3 signaling pathway in glioma." (PMID 31534499, 2019). "Previously, our laboratory reported that there was a significant increase of multiple cytokines including interlukin-6 (IL-6) secreted in glioma-conditioned media from patient-derived adult GBM cell lines which suggested these tumors have increased STAT3 signaling." (PMID 31361777, 2019). "Therefore, Napabucasin blocked survival and self-renewal of glioma stem cells by downregulating the expression of STAT3 and other stemness markers." (PMID 31277685, 2019). "In addition, miR-124 enhances T-cell effector cytokine production via STAT3 signaling and thereby reverses glioma-mediated immunosuppression." (PMID 30644073, 2019). "Activated STAT3 induces miR-182-5p expression, which enhances the growth of gliomas." (PMID 31007608, 2019). "Studies also show that IL-1β can activate STAT3 in osteoblasts, Th17, and glioma." (PMID 31300060, 2019).
glioma (continued). "While C/EBPδ has not previously been associated with drug sensitivity, high expression is known be associated with poor prognosis across glioblastomas and the closely related C/EBPβ is recognized as a synergistic master regulator with STAT3 of the mesenchymal phenotype in aggressive glioma." (PMID 31136571, 2019). "Herein, we discuss current experimental and clinical evidence that highlights the pivotal role of STAT3 in glioma tumorigenesis and particularly in shaping tumor immune microenvironment in an effort to justify the high need of selective targeting for glioma immunotherapy." (PMID 31698775, 2019). "Here we present data showing that the therapeutic application of siRNAs, formulated in nanoscale lipopolyplexes (LPP) based on polyethylenimine (PEI) and the phospholipid 1,2-dipalmitoyl-sn-glycero-3-phosphocholine (DPPC), represents a promising new approach to target Stat3 in glioma." (PMID 30857197, 2019). "ELTD1 promotes the progression of glioma through the JAK/STAT3/HIF-1α axis." (PMID 31554859, 2019). "Another recent approach using a compound drug consisting of an aptamer targeting PDGFbeta and an siRNA targeting Stat3 in glioma showed similar growth retardation in vitro and in vivo, although this study only used subcutaneous xenografts for the in vivo experiments." (PMID 30857197, 2019). "For example, CRNDE can promote glioma progression by attenuating the miR-384/PIWIL4/STAT3 axis." (PMID 31052326, 2019). "In vitro studies have demonstrated the role of Stat3 in glial tumour biology, especially in glioblastoma, being directly involved in maintaining the stem-like phenotype, EMT (epithelial-mesenchymal transition), resistance to alkylating agents such as temozolomide (TMZ) and radiotherapy." (PMID 31690341, 2019). "Expression of STAT3-S727A in glioma increases survival, proliferation and invasion." (PMID 30675525, 2019). "Similarly, exogenous expression of Stat3 inhibited the development of these glioma-like lesions as well." (PMID 30833574, 2019). "Furthermore, it has been demonstrated that glioma cell-derived conditioned medium is able to increase STAT3 activity in microglia cells, leading to increased secretion of the anti-inflammatory M2-like cytokines IL-6 and IL-10." (PMID 29389898, 2018). "The result revealed that STAT3 was up‐regulated in glioma tissues." (PMID 30134017, 2018). "We previously demonstrated that miR-519a functions as a tumor suppressor in glioma by targeting STAT3; therefore, we hypothesized that miR-519a-mediated prodeath autophagy may occur via targeting of STAT3 to sensitize U87-MG/TMZ cells to TMZ." (PMID 29843746, 2018). "Firstly, we manifested the high expression levels of STAT3 in glioma tissues and cell lines." (PMID 30134017, 2018). "To determine whether STAT3 promoted glioma progression via FOXP1 induction, we performed rescue experiment in U87 and SHG‐44 cells." (PMID 30134017, 2018). "This suggests that inhibiting the JAK/STAT3 pathway may be an effective therapeutic strategy for high-grade glioma." (PMID 29164272, 2018). "Consequently, Smad6 reduces PIAS3-mediated STAT3 inhibition and promotes glioma cell growth and stem-like cell initiation." (PMID 29950561, 2018). "Furthermore, inhibition of STAT3 enhances the response of glioma cells to temozolomide and radiation." (PMID 29164272, 2018). "Additionally, reducing glioma cell viability dramatically induced by STAT3 inhibition was rescued via FOXP1 upregulation." (PMID 30134017, 2018). "The molecular mechanisms of STAT3 regulation in glioma remain elusive." (PMID 30134017, 2018). "The current study featured the latent molecular mechanism of STAT3 in glioma cells." (PMID 30134017, 2018). "We further tested whether honokiol can inhibit the stemness of glioma stem cells via the STAT3 signaling pathway." (PMID 30587839, 2018).